HMGB1 (high mobility group box 1)
Diseases named in the same sentence as HMGB1 in open-access papers (continued):
Sharing a sentence is not in itself a finding about the gene and the disease.
atherosclerosis (continued). "Atherosclerosis is an inflammatory disease of the arterial walls, and RAGE has been linked to atherosclerosis development via several ligands, including AGEs, HMGB1, and S100 proteins." (PMID 34199060, 2021). "HMGB1 also promotes atherosclerosis progression with a significant role in cardiovascular disease development." (PMID 34044825, 2021). "HMGB1 has recently been recognized as a determining factor in atherosclerosis formation and development." (PMID 34044825, 2021). "HMGB1 promotes even VSMCs replication, which can justify neointima hyperplasia during atherosclerosis development and restenosis after coronary angioplasty." (PMID 34044825, 2021). "Giving the mice a neutralizing monoclonal antibodies against HMGB1 reduced the development of atherosclerosis by 55%." (PMID 33114431, 2020). "Most of the other intestine specific pathways influenced by alkaloid exposure have a role in the inflammatory response: the inflammasome pathway, HMGB1, and atherosclerosis signaling." (PMID 33062652, 2020). "Atherosclerosis and high mobility group box 1 (HMGB1) signaling and the inflammasome pathway were also depressed (P < 0.001) in the intestinal epithelium of BROMO steers compare with CON steers." (PMID 33062652, 2020). "On the contrary, NLRP3 inflammasome activation accelerates atherosclerosis induced by HMGB1 secretion, indicating that HMGB1 is a key downstream signaling molecule of NLRP3 inflammasome activation." (PMID 32161574, 2020). "Therapeutic blockade of HMGB1 reduced the development of diet-induced atherosclerosis in ApoE−/− mice." (PMID 33371312, 2020). "All these factors promote a pro-inflammatory cytokines milieu, including TNF-α, IL-1β, IL-6- IL-8 and HMGB1, which contribute to endothelial damage, development of atherosclerosis and impaired angiogenesis, leading actors in diabetic vascular complications." (PMID 31835864, 2019). "Compelling evidences indicate that HMGB1, TLR4, and IL-1β are implicated in the progression of atherosclerosis." (PMID 30881312, 2019). "In this study, we demonstrated that CUMS significantly increased atherosclerosis lesions as well as HMGB1 levels both in serum and aortas of ApoE-/- mice." (PMID 30881312, 2019). "Through the linkage to its receptors, HMGB1 promotes ROS formation and it activates the pro-inflammatory cascade responsible of endothelial damage and progression of atherosclerosis." (PMID 31835864, 2019). "In this study, CUMS ApoE-/- mice model with atherosclerosis was established, and HMGB1 inhibitor or TLR4 inhibitor was used to test its role in atherosclerosis under CUMS." (PMID 30881312, 2019). "Hyperglycemic environment affects levels of HMGB1, which is responsible of atherosclerosis progression." (PMID 31835864, 2019). "Our study demonstrates that HMGB1 promotes CUMS-induced atherosclerosis via activating TLR4 signaling, which drownregulates the expression of PPARγ-LXRα-ABCA1." (PMID 30881312, 2019). "Recent studies have explored the role of HMGB1 in the pathophysiology of cardiovascular diseases including ischemic injury, myocardial infarction, endothelial dysfunction, and atherosclerosis." (PMID 31336567, 2019). "Under pathological conditions such as hypoxia, cell death, atherosclerosis and ischaemia-induced angiogenesis and in senescent cells, HMGB1 is upregulated and translocated from the nucleus to the cytoplasm and extracellular space." (PMID 31284269, 2019). "A nuclear protein, high mobility group box 1 (HMGB1), is one of the damage-associated molecular patterns and released from dying adipocytes to potentially promote atherosclerosis and vascular remodeling." (PMID 31234839, 2019). "Based on this, we tended to further investigate the effect of HMGB1/TLR4 signaling on the development of atherosclerosis induced by CUMS." (PMID 30881312, 2019).
atherosclerosis (continued). "HMGB1 has been reported to be an upstream regulator of TF in cultured human aortic endothelial cells in a model of atherosclerosis, and it is a key molecule of inflammation and thrombus." (PMID 29595637, 2018). "Although it is regarded as a particular type of arteriosclerosis with significant differences to native atherosclerosis, many similarities exist regarding histological changes as well as signaling pathways that are involved, including the HMGB1/RAGE axis." (PMID 29615103, 2018). "The present study proposed that HMGB1 participated in oxidative stress-induced atherosclerosis by targeting multipotent vascular stem cells (MVSCs)." (PMID 29951536, 2018). "HMGB1 is abundant in the microenvironment in many chronic diseases such as Alzheimer’s disease, atherosclerosis, seizures, and cancers." (PMID 29696019, 2018). "High mobility group box 1 (HMGB1) is a key inflammatory mediator in atherosclerosis, but if oxidized it loses its activity." (PMID 29951536, 2018). "HMGB1 contributes to the pathogenesis of numerous chronic inflammatory and immunologic diseases in addition to atherosclerosis, such as chronic kidney disease, rheumatoid arthritis, and cancer pathogenesis." (PMID 29561847, 2018). "In fact, as atherosclerosis goes over, more macrophages releasing HMGB-1 are recruited and induce proliferation and migration of VSMCs that in turn increase their self-secretion of HMGB-1 stimulating further their proliferation." (PMID 28789654, 2017). "According to IPA canonical pathways analysis, atherosclerosis signaling was considered as the most essential pathway in cardiovascular signaling while HMGB1 signaling was the most critical players in cellar inflammatory response." (PMID 29133791, 2017). "We also looked at the role of HMGB1 in atherosclerosis, angiogenesis, edema, hyperglycemia as well as its neuroimmunological properties and post-ischemic brain recovery." (PMID 29054968, 2017). "The detailed pathways of the atherosclerosis signaling and HMGB1 signaling including the identified molecular targets were generated by IPA." (PMID 29133791, 2017). "They indicated that neutralization of monoclonal antibodies against HMGB1 lessens atherosclerosis by 55%." (PMID 29054968, 2017). "HMGB1 is a pro-inflammatory cytokine that appears to be involved in atherosclerosis and other cardiovascular diseases." (PMID 27713681, 2016). "Another inflammatory cytokine that is likely to regulate vascular expression of miR-221 in atherosclerosis is high-mobility group B1 (HMGB1; alarmin)." (PMID 26221589, 2015). "It has been previously demonstrated that anti-HMGB1 antibody reduces atherosclerotic lesion pro-inflammatory cells and progression of atherosclerosis in a mouse model." (PMID 26075638, 2015). "The importance of HMGB1 in the development of atherosclerosis has been demonstrated in apoE-/- transgenic mice." (PMID 25884983, 2015). "High serum HMGB1 levels have been observed in infectious diseases, atherosclerosis, mechanical trauma, cancer, and in systemic autoimmune diseases such as systemic lupus erythematosus (SLE)." (PMID 26062541, 2015). "Individuals with subclinical atherosclerosis and cardiovascular (CV) events present high HMGB1 levels whereas atorvastatin decreases serum HMGB1 in hyperlipidemia." (PMID 24776932, 2014). "Previous studies had also shown reduction of HMGB1 levels upon statins in an experimental model of atherosclerosis and in humans with hyperlipidemia." (PMID 24776932, 2014). "Secreted HMGB1 can be neutralized by administering soluble RAGE as discussed for controlling atherosclerosis and inflammation." (PMID 23766911, 2013). "Numerous recent studies have also shown that HMGB1 acts as an inflammatory mediator in cardiovascular diseases, such as atherosclerosis, myocardial ischemia-reperfusion injury, and heart failure." (PMID 22778498, 2012).
atherosclerosis (continued). "High mobility group box 1 (HMGB1), an injury-associated molecular pattern molecule acting as a mediator of inflammation, has recently been implicated in the development of atherosclerosis." (PMID 23284878, 2012). "Empirical studies indicate that HMGB-1 expression increases as atherosclerosis progresses." (PMID 39816684, 2025). "Taken together, HMGB1 is involved in low-density lipoprotein transport, recruitment of inflammatory cells, and exacerbation of the multiple inflammatory effects of HMGB1 on endothelial cells, smooth muscle cells, and macrophages, thereby inducing the onset and progression of atherosclerosis." (PMID 38740617, 2025). "HMGB1 promotes atherosclerosis by negatively regulating the Treg/Th17 ratio." (PMID 38740617, 2025). "Thus, several lines of evidence indicate the involvement of HMGB1 in pathological responses of VSMCs that are correlated with atherosclerosis." (PMID 39194749, 2024). "Additionally, HMGB1 has been found to play a role in the development of atherosclerosis by promoting cell necrosis, but the specific mechanisms need further investigation." (PMID 38493291, 2024). "It is known that HMGB1 plays significant role in the pathogenesis of atherosclerosis." (PMID 39457420, 2024). "Therefore, current evidence demonstrates the greater presence of HMGB1 in patients with atherosclerosis or in conditions that lead to the progression of the vascular disorder." (PMID 39194749, 2024). "Importantly, numerous ncRNAs regulate the expression of HMGB1, and several studies have investigated these signalling axes in the context of atherosclerosis and VSMCs." (PMID 39194749, 2024). "HMGB1 participates in endothelial dysfunction by binding to the receptor for advanced glycation end products and toll-like receptors, indicating that HMGB1 is highly related to the development of atherosclerosis." (PMID 39596269, 2024). "Additionally, HMGB1 promotes atherosclerosis development and progression by promoting smooth muscle cell migration and proliferation." (PMID 37062906, 2023). "High mobility group box 1 (HMGB1) is a damage-associated molecular pattern (DAMP), secreted from endothelial cells and leukocytes that mediate inflammation, and correlates with the severity of atherosclerosis." (PMID 36768748, 2023). "Higher serum HMGB1 levels are considered to be a potential marker of subclinical atherosclerosis." (PMID 36704514, 2022). "Also, the major DAMPs including HMGB1 and S100B and their downstream signaling via TLR4 receptor have been intimately associated with the aggravated atherosclerosis resulting in the upregulation of proinflammatory cytokines including IL-18 and IL-1β." (PMID 35531433, 2022). "The induction in EV level of HMGB1 by one night of SD suggests that this may be one mechanism by which such SD may promote platelet contributions to thrombosis and atherosclerosis." (PMID 36043452, 2022). "Based on these, we propose the hypothesis that QB can reduce the inflammatory response and delay disease progression in SLE combined with atherosclerosis by inhibiting the HMGB1/TLR4/MyD88 pathway." (PMID 35571092, 2022). "In the inflammatory state of cardiovascular disease, HMGB1 as a proinflammatory cytokine derived from injured endothelium and activated macrophages/monocytes may play a role in atherosclerosis and other cardiovascular disorders." (PMID 35340325, 2022). "Notably, high HMGB1 levels can also be detected in the serum and diseased tissues of patients with atherosclerosis-related diseases such as diabetes, ischemic stroke, and hypertension." (PMID 36544080, 2022). "Interesting data suggests that in ApoE-/-mice, monoclonal anti-HMGB1 neutralizing antibodies reduced atherosclerosis, macrophages, smooth muscle and dendritic cell accumulations, and they reduced vascular cell adhesion molecule-1 and monocyte chemoattractant protein-1 expression." (PMID 34044825, 2021).
atherosclerosis (continued). "Furthermore, in atherosclerosis, HMGB1 has been shown to modulate Treg/IL17 ratio through inducing apoptosis in Tregs and promoting Th17 cells differentiation." (PMID 33679792, 2021). "The present study aimed to confirm miRNAs associated with atherosclerosis and explore the molecular mechanism of miR‐34c and its target high mobility group box protein 1 (HMGB1) in the control of growth of smooth muscle cells in the development of atherosclerosis." (PMID 32157741, 2020). "Our results suggest that NF-κB activation may be involved in HMGB1–RAGE-mediated atherosclerosis in OSA." (PMID 32076951, 2020). "This makes HMGB1 inhibition potentially effective theraputic approach to atherosclerosis." (PMID 32208365, 2020). "This suggests that platelet-derived HMGB1 may be involved in the progression of both atherosclerosis and atherosclerotic thrombosis." (PMID 33371312, 2020). "Above reports confirmed the role of HMGB1 in inflammation as well as in atherosclerosis." (PMID 31336567, 2019). "HMGB1 promotes inflammatory response functioning as an essential facilitator in inflammatory diseases and has an important role in the pathophysiology of atherosclerosis." (PMID 32063860, 2019). "It has been hypothesized that high mobility group box 1 protein (HMGB1) may play a crucial role in the oxLDL-induced development of atherosclerosis." (PMID 31277498, 2019). "Moreover, with development of atherosclerosis from fatty streaks to fibro-fatty lesion, the number HMGB1-producing macrophages considerably increase in atherosclerotic plaque, demonstrating a role of HMGB1 in disease progression." (PMID 31835864, 2019). "Therefore, our study provided a novel mechanism that CUMS-induced HMGB1 promotes atherosclerosis via TLR4." (PMID 30881312, 2019). "Given that, we therefore ask whether and how HMGB1 regulates TLR4-mediated inflammation in atherosclerosis induced by CUMS." (PMID 30881312, 2019). "Therefore, we postulated a novel mechanism linking oxidative stress to atherosclerosis, which considered HMGB1 as a critical regulator in oxidative stress-induced vascular injury." (PMID 29951536, 2018). "Therefore, the findings suggested that HMGB1 participated in oxidative stress-induced atherosclerosis presumably by targeting multipotent vascular stem cells." (PMID 29951536, 2018). "Similarly, HMGB1-specific antibodies are protective against ischemia/reperfusion, trauma, chemical toxemia, atherosclerosis, gastric ulcer, and hyperoxia, supporting the pathogenic role of HMGB1 in injury-elicited inflammatory diseases." (PMID 25821489, 2015). "Inhibition of PARP-1 may shed light on the treatment of HMGB1 involved inflammation during atherosclerosis." (PMID 25793984, 2015). "Nonetheless, it remains unknown if SOCE exerts control over endothelial hyperpermeability regulated by HMGB1 in atherosclerosis." (PMID 25884983, 2015). "Inhibition of PARP-1 might shed light on the treatment of HMGB1 involved inflammation during atherosclerosis." (PMID 25793984, 2015). "However, the precise mechanisms by which HMGB1 regulates endothelial hyperpermeability in atherosclerosis remain to be established." (PMID 25884983, 2015). "We hypothesized that serum HMGB1 levels contribute to subclinical atherosclerosis in GPA and that this process is influenced by sRAGE but also by treatment with prednisolone and statins." (PMID 24776932, 2014). "Therefore, it is possible that the HMGB1/RAGE axis contributes to the pathogenesis of atherosclerosis." (PMID 24065095, 2013). "Indeed, a link has already been drawn between HMGB1 and the PGE2 pathway in a study on the involvement of HMGB1 in the pathology of atherosclerosis." (PMID 23488692, 2013).
atherosclerosis (continued). "However, treatment with anti-HMGB1 McAb attenuates atherosclerosis, macrophage accumulation in atherosclerotic lesions, and expression of VCAM-1, MCP-1, TNF-α, and interleukin-1β in diabetic apoE(−/−) mice." (PMID 24065095, 2013). "Furthermore, neutralising HMGB1 attenuated the development of atherosclerosis in an animal model of atherosclerosis." (PMID 22752054, 2012). "Smooth muscle cells, endothelial cells, foam cells, macrophages, and activated platelets in atherosclerotic plaques may secrete HMGB1, exacerbating the multiple inflammatory effects of HMGB1 on endothelial cells, smooth muscle cells, and macrophages and the progression of atherosclerosis." (PMID 38740617, 2025). "The effect of HMGB1 on atherosclerosis may also be related to its redox status." (PMID 37062906, 2023). "HMGB1 participates in the pathological process of atherosclerosis by binding to the receptor for advanced glycation end-product (RAGE) and toll-like receptors (TLRs) indicating HMGB1 may be highly correlated with the occurrence and development of atherosclerosis." (PMID 36544080, 2022). "Furthermore, Wang and colleagues demonstrated that LPS/ATP activation of NLRP3 inflammasome stimulates HMGB-1 release leading to cholesterol accumulation in VSMCs and foam cells formation during atherosclerosis, through the downregulation of LXRa and ABCA1 expression." (PMID 36244983, 2022). "Because administration of anti-HMGB1-neutralizing antibody reduces atherosclerosis in mice and a peptide that antagonizes B box cytokine activity prevents cancer progression (45, –, 47), blockade of HMGB1 could be an effective therapeutic strategy for treating these diseases." (PMID 28373282, 2017). "Therefore, the HMGB1/RAGE axis may contribute to the pathogenesis of atherosclerosis, and inhibition of the HMGB1/RAGE axis may offer a novel option for treatment of atherosclerosis." (PMID 24065095, 2013). "In this study, we analyzed the demise of HAEC induced by C. pneumoniae, including the release of HMGB1 at the level of the individual cell in order to elucidate whether the pathogen might contribute to the initial endothelial damage occurring in atherosclerosis." (PMID 18284660, 2008). "Hsa_circ_0031891 promotes PDGF-BB-induced human aortic VSMCs proliferation, migration, and dedifferentiation partly via regulating the miR579-3p/high-mobility group box 1 (HMGB1) axis, suggesting a potential therapeutic strategy for atherosclerosis." (PMID 39595622, 2024). "It is known that lipid transport proteins (CAV-1, ABCA1, SREBP-1, LXR, etc.)and inflammation (HMGB1, CXCL13, TIMP-1, etc.)in blood vessels mediate the formation of atherosclerosis." (PMID 38622667, 2024). "QA inhibits the increase of cholesterol, TMA, TMAO, CXCL13, TIMP-1 and HMGB1 levels in peripheral blood of Apoe−/− mice induced by HFD, suggesting that QA can effectively inhibit HFD-induced atherosclerosis." (PMID 38622667, 2024). "Reduced‐HMGB1 can inhibit pluripotent vascular stem cell proliferation and differentiation, whereas oxidized‐HMGB1 loses its ability to inhibit the proliferation and differentiation of these cells, indicating that HMGB1 with different redox states may regulate atherosclerosis." (PMID 37062906, 2023). "Toll-like receptor 4 (TLR4), a transmembrane non-catalytic protein expressed on the cell surface, is a downstream target of HMGB1 and is involved in the induction of the inflammatory program and in the progression of SLE and atherosclerosis." (PMID 35571092, 2022). "High mobility group box-1 (HMGB1) is a nuclear protein involved in promotion and progression of atherosclerosis and cardiovascular diseases." (PMID 34044825, 2021).